INS (insulin)
Diseases named in the same sentence as INS in open-access papers (continued):
Sharing a sentence is not in itself a finding about the gene and the disease.
diabetes (continued). "In order to achieve this aim, this section is designed to review not only antioxidant functions, but also the role of antioxidants in obesity, dyslipidemia and adipose tissue remodeling, diabetes and insulin metabolism, hypertension, and endothelial function." (PMID 38892574, 2024). "The glucose-responsive smart systems are particularly useful for patients with insulin-dependent diabetes mellitus since insulin discharge from them is controlled by blood glucose levels." (PMID 38167129, 2024). "The significant coincident risk factors for DSPN detected by 6- and 2-point MNSI were older age, Aboriginal ethnic background, greater height, diabetes duration, insulin treatment, and higher uACR." (PMID 37930807, 2024). "Over the past two decades, insulin glargine 100 U/mL (Gla-100) has emerged as the “standard of care” basal insulin for the management of type 1 diabetes mellitus (T1DM)." (PMID 36896906, 2024). "Preservation of islet β-cells and release of insulin from β-cells are another beneficial effect of RSV on diabetes." (PMID 38716357, 2024). "Historically, the discovery of insulin in 1921 revolutionized diabetes treatment, significantly extending patient life expectancy." (PMID 39840001, 2024). "Although the area of therapeutic approaches for AD as “type 3 diabetes” is still developing, treatments using common diabetes medications, insulin administration, and targeted therapeutic strategies exist." (PMID 39596023, 2024). "Risk stratification for type 2 diabetes is often solely based on clinical measures such as HbA1c, blood pressure, presence of diabetes-related complications, and insulin use." (PMID 38312481, 2024). "Recent mHealth interventions targeting diabetes are diverse in their goals and components, and include insulin management applications, wearable GMDs, automated text messages, health diaries and virtual health coaching." (PMID 39281234, 2024). "Lewis D. Understanding Automated Insulin Delivery: A basic book for kids, family, and friends of people living with diabetes." (PMID 39196351, 2024). "Diabetes affects the transfer of glucose and insulin through the blood-brain barrier 37, thereby affecting regional metabolism and microcirculation." (PMID 39006846, 2024). "Such a sharp decline in the effective production of insulin directly affects the self-repairing capacity of diabetes patients." (PMID 39619638, 2024). "Confusion about the different types of diabetes and the use of insulin was observed in most of the focus groups." (PMID 38397639, 2024). "Diabetes mellitus (DM) is a metabolic condition that is typically characterized by inadequate production of insulin or dysfunction in the insulin receptors, leading to persistently high levels of glucose in the blood." (PMID 39605919, 2024). "It is imperative to control diabetes with insulin or oral hypoglycemic therapies to ensure the life of people with diabetes while simultaneously minimizing the progression of diabetic complications, promoting increased life expectancy and quality of life." (PMID 39767558, 2024). "IL-6 cytokine is also involved both in diabetes and cancer by controlling glucose homeostasis, insulin sensitivity as well as tumorigenesis in different cancers." (PMID 39333445, 2024). "The phenotype of Gcgrβ-cell−/− animals is altered first-phase insulin secretory responses during an intravenous glucose challenge, redolent of pre-diabetes." (PMID 38677509, 2024). "Topic7 pertains to diabetes management, with keywords including insulin, glucose, diabetes, diabetic, humalog, lantus, and hyperglycemia." (PMID 39336990, 2024). "Compared with patients with 1-vessel disease, the duration of diabetes, use of insulin, SD-HbA1c, and HbA1c were increased, and HbA1cTIR was decreased in patients with multiple vessel disease." (PMID 39118831, 2024).
diabetes (continued). "Type 2 diabetes mellitus is a chronic metabolic disorder resulting from a combination of the inability of the muscle cells to react to insulin (insulin resistance) and inadequate compensatory insulin secretion." (PMID 39767546, 2024). "Lower adherence was associated with factors such as illiteracy, low income, rural residence, unemployment, longer duration of diabetes, insulin therapy, less frequent clinic visits, a higher medication burden, and an increased prevalence of complications." (PMID 39469399, 2024). "Both the GDM and preexisting diabetes groups exhibited elevated pre-pregnancy BMI; however, insulin requirements were significantly greater among women with preexisting diabetes." (PMID 40071056, 2024). "Diabetes mellitus is a major endocrine disease in which the pancreas produces insufficient insulin or the produced insulin cannot bind with the appropriate receptor." (PMID 39201724, 2024). "Nevertheless, it's crucial to recognize that physicians have a pivotal role to fulfill in the initiation of insulin therapy for effectively managing patients with poorly controlled diabetes." (PMID 38910730, 2024). "Diabetes mellitus (DM) is a multifaceted metabolic condition marked by high blood sugar levels, resulting from either inadequate insulin production or diminished insulin sensitivity." (PMID 39683476, 2024). "Extensive research has delved into chrysin’s capacity to restore insulin sensitivity and its effects on diabetes." (PMID 38474354, 2024). "Concerning complexity of diabetes treatment and impact of insulin therapy on daily life, numerous studies exploring patients’ perceptions on insulin treatment were conducted." (PMID 38610878, 2024). "Notable advancements include the development of inhaled insulin, which offers a non-invasive alternative to subcutaneous injections for diabetes management." (PMID 39006724, 2024). "Its role in diabetes treatment is significant, as it induces insulin secretion, suppresses glucagon secretion, slows down gastric emptying, and decreases appetite and food intake." (PMID 39220011, 2024). "These stable interactions suggest a potential for lactoferrin to modulate inflammation and improve insulin sensitivity, offering avenues for preventive and therapeutic interventions in diabetes." (PMID 39092264, 2024). "Societal-level barriers include high costs of insulin, other medications, and supplies; limited access to healthcare and insurance; and diabetes-related stigma." (PMID 39867016, 2024). "The mean duration of diabetes in DR patients was 2031 months (ranging from 1 to 480 months), and 69% of patients required insulin medication." (PMID 38892258, 2024). "Diabetes mellitus involves both insufficient insulin secretion and dysregulation of glucagon secretion." (PMID 39313541, 2024). "Treatment with NPH and glargine insulin at a dose of 150 mg/kg of alloxan-induced diabetes required less insulin administration than 200 mg/kg of alloxan." (PMID 39070316, 2024). "Their findings indicate that prolonged Gck overexpression leads to increased hepatic lipogenesis and circulating lipid levels, potentially contributing to an insulin-resistant phenotype and diabetes onset in these mice." (PMID 39245718, 2024). "Conversely, this resistance to insulin results in metainflammatory and OS within the body, ultimately leading to diabetes." (PMID 39493064, 2024). "Of those with diabetes, 19,597 (17%) were managed with diet only, 58,828 (52%) were managed with oral hypoglycaemic medication and 34,130 (30%) were treated with insulin." (PMID 39358593, 2024). "Using multi-metabolite monitoring data to adjust insulin delivery holds the promise to substantially improve the quality of life of people with diabetes." (PMID 38701088, 2024).
diabetes (continued). "What’s more, researchers suggested that targeting cannabinoid (CB) receptors/modulating the degree or activity of endocannabinoids in tissue is beneficial to decrease insulin/leptin resistance in diabetes and mitigate the myocardial damage during I/R phase." (PMID 39538244, 2024). "In modern medicine, drugs for treating diabetes mainly include the following categories: insulin sulfonylureas, α-glucosidase inhibitors, insulin sensitizers and insulin secretors." (PMID 38921004, 2024). "Diabetes Mellitus (DM) is a metabolic disease characterized by persistenthyperglycemia resulting from defects in insulin secretion by pancreatic beta cellsor decreased sensitivity to insulin by other cells in the body." (PMID 39133695, 2024). "Aerobic (endurance) and resistance exercise play crucial roles in improving glycemic control and insulin sensitivity in individuals with diabetes." (PMID 39795939, 2024). "A recent study demonstrated diabetes protection in the highly aggressive VH125Tg.NOD model when mice were treated with the insulin–Fc fusion drug, AKS-107." (PMID 38651407, 2024). "Insulin pump therapy has emerged as a cornerstone of diabetes management, offering a continuous supply of insulin through subcutaneous infusion with greater flexibility and precision when compared to standard insulin injections." (PMID 39065641, 2024). "A study of CGM in patients with diabetes (median age, 82 years) found at least one episode of hypoglycemia (<70 mg/dL) during a 5‐day period in 33% of insulin‐treated patients and in 44% of patients on other hypoglycemic drugs." (PMID 39375857, 2024). "Diabetes mellitus (DM) is a chronic and complex metabolic disorder that results from a defect in insulin secretion, action, or both." (PMID 38966213, 2024). "As expected, the proportion of people on insulin therapy increases with an increasing duration of diabetes and the occurrence of complications." (PMID 39081469, 2024). "Exploring the effects of COVID-19 on patients with diabetes, we found that the novel coronavirus damages islet β cells, leading to reduced insulin secretion, triggering cytokine-induced insulin resistance, and making blood glucose control more difficult." (PMID 38975064, 2024). "The effects of zinc on diabetes mellitus are dose-dependent, with appropriate supplementation showing promise in improving glycemic control and insulin sensitivity." (PMID 39195249, 2024). "Diabetes is characterized by chronic hyperglycemia, resulting from either insufficient insulin production or the body's resistance to insulin's effects." (PMID 39720384, 2024). "Managing diabetes imposes lifestyle changes such as adhering to a strict diet, regularly monitoring blood glicose levels, and consistently taking medication or insulin therapy." (PMID 39845677, 2024). "In diabetes, oxidative stress impairs insulin signalling and damages pancreatic β-cells, reducing glucose uptake and insulin secretion, thereby worsening the disease." (PMID 39204080, 2024). "The usage of insulin, medication, and particular diets are among the therapeutic alternatives that have been accessible for the control of diabetes for the past few decades." (PMID 38926327, 2024). "On the other hand, ME extract reduced the incidence of diabetes and preserved normal insulin secretion." (PMID 38675115, 2024). "VD influences the pathophysiology of diabetes by enhancing insulin synthesis and secretion, improving insulin sensitivity, and reducing oxidative stress, inflammation, and DNA methylation." (PMID 39519484, 2024). "When considering the effects of SGLT2 inhibition on diabetes treatment, it is important to note that this leads to enhanced insulin responsiveness and beta-cell activity." (PMID 39211720, 2024). "The distribution of patients having diabetes and a history of insulin use was similar between the two groups." (PMID 38698018, 2024).
diabetes (continued). "We observed a significant decrease in the expression of insulin and β cell damage in situ in the pancreatic section, consistent with the typical histological damage in clinical diabetes patients." (PMID 38609366, 2024). "Multicollinearity was observed between insulin use and self-reported diabetes (variance inflation factor VIF >10)." (PMID 38381882, 2024). "One PCP reported one of their patients with diabetes finally agreed to start with insulin, and because of this now has good glycemic values." (PMID 38759017, 2024). "We measured the effect of betaine co-administration with the HF diet, as well as betaine administration after development of diabetes and fatty liver, on in vivo glucose metabolism and hepatic insulin signaling pathways." (PMID 39119463, 2024). "Diabetes mellitus (DM) is defined as a chronic metabolic disorder that is characterized by the body's incapacity to produce or effectively utilize insulin, a hormone that is crucial for controlling blood glucose levels." (PMID 39308841, 2024). "The aim of this study was to compare the hypoglycemic effect of insulin-loaded NPs to that of subcutaneous insulin in an in vivo rat model of diabetes." (PMID 38813352, 2024). "In the future, artificial intelligence/machine learning can be applied to provide personalized long-acting and rapid-acting dosing recommendations that fine-tune insulin therapy settings, further reducing the burden of diabetes management." (PMID 37855818, 2024). "Nonetheless, the ability of seaweed peptides to mimic the action of insulin and regulate blood sugar levels represents a significant opportunity for the development of new treatments for diabetes." (PMID 38667785, 2024). "For metabolic disorders, oxidative stress disrupts insulin signalling and lipid metabolism, fostering obesity and diabetes." (PMID 39204080, 2024). "Type 1 diabetes (T1D) simulators, crucial for advancing diabetes treatments, often fall short of capturing the entire complexity of the glucose-insulin system due to the imprecise approximation of the physiological models." (PMID 38493243, 2024). "Small molecule and light-inducible therapeutic systems cannot accurately control blood glucose and achieve rapid insulin expression in diabetes treatment." (PMID 37847216, 2024). "The evolving understanding of type 2 diabetes mellitus (T2DM) as a bi-hormonal disorder involving both insulin and glucagon suggests the potential characterization of T2DM as a multi-hormonal disorder with further exploration into the role of NAB cells." (PMID 38371125, 2024). "Recent research indicates that miRNAs play a crucial role in modifying cellular pathways, namely, β cell survival, function, and peripheral insulin signaling, which are related to the onset and development of diabetes (primarily T2DM)." (PMID 39595541, 2024). "Exercise in patients with diabetes treated with insulin or medication improving insulin secretion (e.g., sulfonylurea) requires specific attention." (PMID 38414660, 2024). "The absolute or relative insufficiency of insulin secretion is a characteristic feature of all common forms of diabetes mellitus." (PMID 39396974, 2024). "During aging, or the development of obesity and diabetes, the whole-body insulin response generally shifts to the right, and the right-shift is regarded as a sign of insulin resistance and is construed as a defect of insulin receptor function." (PMID 39617270, 2024). "The study found that among patients who developed diabetes before the age of 30 and were treated with insulin, the prevalence of DR Was 71%, the cumulative 4-year prevalence was 59%, and 11% of patients progressed to PDR." (PMID 38645437, 2024). "PTP1B is a promising target for diabetes control due to its role in the development of insulin resistance, where it plays a key role in regulating insulin signaling." (PMID 39275157, 2024).
diabetes (continued). "These compounds play a vital role in regulating blood glucose levels, enhancing insulin secretion, and protecting pancreatic cells from damage, positioning M. calabura as a promising natural product for diabetes management." (PMID 39050386, 2024). "Cases were older, more often male, daily insulin users, had diabetes for longer, had higher systolic blood pressure, had a lower body mass index (BMI) and HDL cholesterol, and had more impaired renal function than the controls." (PMID 39408563, 2024). "After aggressive treatment to correct diabetic ketoacidosis, the patient’s blood glucose levels stabilized and symptoms of diabetes improved significantly, although long-term insulin maintenance therapy was necessary." (PMID 38247005, 2024). "Elevated blood glucose levels arising from either insulin insensitivity, inadequate insulin release, or a blend of both circumstances are the features of diabetes mellitus, a common chronic metabolic illness." (PMID 39771551, 2024). "It found inadequate dedicated centres for diabetes care, limited laboratory tests, equipment, and poor supply of medications especially insulin." (PMID 38768080, 2024). "Patients with diabetes who were overweight or obese received higher doses of insulin, particularly in IU/m2/day." (PMID 39768947, 2024). "IL-15 has been reported as a myokine that improves fatty acid utilization, insulin sensitivity, and endurance capacity, and prevents obesity and diabetes." (PMID 38913071, 2024). "According to the different responses to insulin, diabetes can be divided into type I diabetes and type II diabetes: the proportion of type I diabetes complicated with DN is about 35%, while the proportion of type II diabetes complicated with DN is about 22%." (PMID 38645437, 2024). "The results of the present study highlighting the association between TIR and the S-CPR index reaffirmed the importance of early diagnosis and therapeutic interventions for diabetes to prevent impairment of insulin secretory capacity." (PMID 38839813, 2024). "The proposed mechanisms by which vitamin D appears to be protective against diabetes include increasing insulin secretion, improving insulin sensitivity, and reducing systemic inflammation." (PMID 38956028, 2024). "Adiponectin is a protective hormone against diabetes, since it promotes insulin sensitivity and also protects endothelium from redox damage." (PMID 38327565, 2024). "None of our index variants were in LD with a diabetes variant and only one (AR/EDA2R locus) was in LD with fasting insulin as a diabetes related trait." (PMID 38233393, 2024). "Since its discovery, insulin therapy has represented a mainstay in the therapy of diabetes, including T2D, where insulin supplementation is often needed to achieve glucose control." (PMID 38767675, 2024). "Subsequently, the pancreatic insulin secretion capacity is impaired, ultimately leading to the development of diabetes." (PMID 39050759, 2024). "In this study, we observed that the combination of vitamin D supplementation and insulin treatment resulted in improved diabetes biomarkers in type 2 patients with microvascular complications." (PMID 38216955, 2024). "Diabetes mellitus (DM) refers to a range of metabolic dysfunctions marked by chronic hyperglycemia due to impaired insulin efficacy, insufficient insulin secretion, or both of them." (PMID 39599740, 2024). "The insulin used for the clinical treatment of diabetes is mainly biosynthetic human insulin or its analogs." (PMID 39190215, 2024). "The most used diabetic therapy is Metformin, which improves insulin sensitivity to treat pre/diabetes in PCOS and increase quality of life." (PMID 39479136, 2024). "Type 2 diabetes mellitus (T2DM) is a complicated disease related to metabolism that results from resistance to insulin and sustained hyperglycemia." (PMID 38783768, 2024).